MYD88 (MYD88 innate immune signal transduction adaptor)
Diseases named in the same sentence as MYD88 in open-access papers (continued):
Sharing a sentence is not in itself a finding about the gene and the disease.
leishmaniasis (3 papers, 2022 to 2024). Infectious disease that is transmitted through the bite of hematophagous female phlebotomine sand flies. "In a mouse model, deletion of both TLR9 and MyD88 promoted lesion progression and increased levels of Th2-associated cytokines (IL-4 and IL-13) in leishmaniasis, which suggests that TLR9 and MyD88 play crucial roles in the Th1-mediated healing response against L. guyanensis." (PMID 36633419, 2023).
lung adenocarcinoma (3 papers, 2018 to 2024). A carcinoma that arises from the lung and is characterized by the presence of malignant glandular epithelial cells. "Galectin-3 reportedly serves as a ligand of TLR4 and promotes TLR4, MyD88 and p-p65 expression; we investigated whether Galectin-3 could modulate lung adenocarcinoma cell proliferation and migration through TLR4/NF-κB/NEAT1." (PMID 29788922, 2018). "In lung adenocarcinoma, LPS stimulation also caused a remarkable increase in TLR4, MyD88 and p-p65 protein expression, as well as NEAT1 mRNA expression, which could be partially reversed by CLI-095, an inhibitor of TLR4 signaling." (PMID 29788922, 2018). "To test conservation of the function of SPOP in downregulating MyD88, we constructed expression vectors with SPOP of human and mouse origin and respectively transfected the plasmid into human lung adenocarcinoma cells (A549 cells) and CHO cells." (PMID 32365080, 2020).
measles (3 papers, 2011 to 2023). A highly contagious viral infection caused by the measles virus. "Furthermore, there are strong associations between this TLR3 SNP and the differences in the downstream intracellular signaling molecules Myeloid Differentiation factor 2 (MD-2) and Myeloid Differentiation Primary Response 88 (MyD88) in both antibody and cellular responses to measles immunization." (PMID 37510216, 2023). "In a related morbillivirus, SNPs in TLR 3, 4, 5, 6 and associated signalling molecules like Myeloid differentiation primary response gene 88 (MyD88) and MD2 affected immune responses to the measles vaccine in human subjects." (PMID 25369126, 2014). "Associations between SNPs in TLRs 3, 4, 5 and 6 and the downstream intracellular signaling molecules, MyD88 and MD2, with variations in both antibody and cellular responses following measles vaccination have been recently described." (PMID 21933421, 2011).
migraine (3 papers, 2019 to 2022). "The TLR4 signaling was observed in initiating and maintaining migraine-like behavior through myeloid differentiation primary response gene 88 (MyD88) in the mouse." (PMID 34576297, 2021). "This study thus provides the firstevidence for involvement of TLR4 signaling through MyD88 in initiatingand maintaining migraine-like behavior and nucleus caudalis neuronalactivation in the mouse." (PMID 31342858, 2019). "In summary, the kynurenine pathway of l-Trp metabolism may be involved in IBS pathogenesis by various mechanisms, including TLR stimulation, which may be also important in migraine through MyD88 activation." (PMID 34576297, 2021). "The aim of this review is to justify the view that KP modulation may provide common triggers for migraine and FGIDs with the involvement of TLR, AhR, and MyD88 activation." (PMID 34576297, 2021).
multiple sclerosis (3 papers, 2012 to 2019). A progressive autoimmune disorder affecting the central nervous system resulting in demyelination. "We previously demonstrated that MyD88 plays a critical role in EAE, the murine model of multiple sclerosis, and showed that the MyD88 BB-loop decoy peptide RDVLPGT ameliorates EAE." (PMID 29930295, 2018).
Neonatal sepsis (3 papers, 2021 to 2022). Systemic inflammatory response to infection in newborn babies. "An overexpression of MYD88 was associated with a poor prognosis of neonatal sepsis; However, our study found that a higher expression of MYD88 was associated with a better prognosis." (PMID 36618365, 2022). "A previous study has found that high circulating MyD88 levels are related to the poor prognosis in patients with neonatal sepsis." (PMID 35571255, 2022).
non-small cell lung carcinoma (3 papers, 2022 to 2025). A group of at least three distinct histological types of lung cancer, including non-small cell squamous cell carcinoma, adenocarcinoma, and large cell carcinoma. "The current study aims to evaluate the effects of interleukin-1β (IL-1β)-mediated lncRNA cardiac hypertrophy-related factor (CHRF)/microRNA-489 (miR-489)/myeloid differentiation factor 88 (Myd88) on non-small-cell lung cancer (NSCLC)." (PMID 35711847, 2022). "For instance, in human non-small cell lung cancer (NSCLC), Annexin A2 (ANXA2) signals through the TLR2/MYD88 axis in neutrophils, inducing ARG1 mRNA expression through amino acid depletion, which in turn inhibits T-cell viability." (PMID 40342932, 2025).
osteomyelitis (3 papers, 2019 to 2022). An acute or chronic inflammation of the bone and its structures due to infection with pyogenic bacteria. "Based on the robust early inflammatory responses to S. aureus in bone coupled with the detection of multiple IL-1 associated cytokines, we focused on the role of MyD88 and IL-1R signaling in coordinating antibacterial defenses during osteomyelitis." (PMID 30978245, 2019). "To determine the contribution of MyD88 and IL-1R signaling towards antibacterial immune responses during S. aureus osteomyelitis, we infected mice globally deficient in MyD88, IL-1R, IL-1α, and IL-1β and measured bacterial burdens and morbidity." (PMID 30978245, 2019). "These experiments confirm that MyD88 is critical for the control of bacterial burdens and systemic dissemination during osteomyelitis independently of any confounding variables associated with separate colony maintenance." (PMID 30978245, 2019). "Data presented in this study highlight MyD88 and IL-1R signaling as critical pathways supporting anti-staphylococcal immunity in bone, but also implicate these signaling cascades in promoting bone loss during osteomyelitis." (PMID 30978245, 2019). "Our findings reveal that while MyD88 and IL-1R signaling are necessary for antibacterial responses in bone, they also contribute to S. aureus-stimulated osteoclastogenesis and host-mediated bone loss during osteomyelitis." (PMID 30978245, 2019). "When considered in concert with recent studies suggesting that the microbiome may regulate bone mass, these observations prompted us to breed Myd88-/- and Myd88+/+ littermate controls from a heterozygous colony and compare these littermate controls for susceptibility to osteomyelitis." (PMID 30978245, 2019). "Given the central role for the signaling adapter MyD88 in pathogen recognition and induction of innate immune responses, we first sought to determine how MyD88 signaling influences staphylococcal burdens and host morbidity and mortality during osteomyelitis." (PMID 30978245, 2019). "In contrast to the extreme systemic morbidity observed in MyD88-/- mice suffering from osteomyelitis, Il1r1-/- mice had less morbidity when compared to WT mice, in that they lost significantly less weight over the course of infection." (PMID 30978245, 2019). "We show that IL-1 is abundantly produced in bone in response to S. aureus infection, and that MyD88 and IL-1R signaling are required to limit staphylococcal burdens during osteomyelitis." (PMID 30978245, 2019). "Taken together, these data demonstrate a critical role for MyD88-dependent immune responses during S. aureus osteomyelitis." (PMID 30978245, 2019). "Although bacterial inocula up to 106 CFUs did not cause mortality in WT mice, Myd88-/- mice were exquisitely susceptible to S. aureus osteomyelitis, with mortality observed even at inocula as low as 104 CFUs." (PMID 30978245, 2019). "Moreover, the extensive repertoire of innate receptors that signal through MyD88 (e.g. TLRs) likely promote a more effective antibacterial response to S. aureus, as MyD88 signaling is critical to prevent disseminated disease and death during osteomyelitis." (PMID 30978245, 2019). "Given that the adapter protein MyD88 is necessary to relay signals from other upstream receptors including TLRs, future studies should explore the relative contributions of other MyD88-dependent receptors in the pathogenesis of osteomyelitis." (PMID 30978245, 2019). "In line with results from mice bred in separate colonies, significant mortality from osteomyelitis was observed in male Myd88-/- mice, but not Myd88+/+ littermate controls." (PMID 30978245, 2019).
ovarian tumour (3 papers, 2012 to 2025). "Our study profiled the status of MyD88 in ovarian tumour samples, and showed the clinicopathological significance of tumour cell self-MyD88 expression in EOC." (PMID 22533866, 2012). "Collectively, the TLR4+/MyD88- phenotype was associated with all types of tissue, including non-dysplastic epithelium, while TLR4+/MyD88+ (co-expression) was associated only with ovarian neoplasms." (PMID 24977712, 2014). "The aim of this study was to comprehensively characterise the distribution and clinical significance of TLR4 and MyD88 expression in a cohort of ovarian neoplasms, which includes all common histologic subtypes and represents the largest such series studied to date." (PMID 24977712, 2014).
pyelonephritis (3 papers, 2009 to 2025). An inflammatory process affecting the kidney. "Kidney macrophages from mice with pyelonephritis induced by TcpC-secreting UPEC showed significantly decreased MyD88 protein levels." (PMID 33788895, 2021). "In order to discover novel polymorphisms associated with UTIs, we PCR-amplified and sequenced the coding regions of 7 TLR pathway genes (TLR2, TLR4, TLR5, MYD88, TIRAP, TRIF, and TRAM) in subjects with a high frequency of cystitis or pyelonephritis episodes." (PMID 19543401, 2009). "In addition to its interaction with MyD88, TcpC also lowered MyD88 levels in kidney macrophages isolated from mice with CFT073-induced pyelonephritis and enhanced co-localization of MyD88 with the proteasome marker PSMD24." (PMID 41310197, 2025).
renal carcinoma (3 papers, 2019 to 2022). A carcinoma arising from the epithelium of the renal parenchyma or the renal pelvis. "The inhibition of NLRP3, as well as of the oligomerization of the myeloid differentiation primary response gene 88 (MyD88), reduces the cardiotoxicity and increases the anticancer properties of sunitinib, in renal cancer-bearing mice." (PMID 35530309, 2022). "In renal cancer cells and cardiomyocytes polydatin reduces expression of pro-inflammatory cytokines and chemokines involved in myocardial damages and chemoresistance and down-regulates the signaling pathway of NLRP3 inflammasome, MyD88 and NF-κB." (PMID 34178667, 2021).
rosacea (3 papers, 2016 to 2025). A chronic erythematous skin disorder that affects the face. "Importantly, the TLR2/Myeloid differentiation factor-88 adaptor protein (MyD88)/NF-κB is implicated in rosacea pathogenesis, as suggested by elevated MyD88 levels in rosacea skin biopsies." (PMID 39351216, 2024). "Our findings confirmed that LL37 induces mast cell activation through the TLR2/MyD88 signaling pathway, promoting the release of inflammatory mediators and chemokines that drive rosacea pathology." (PMID 41383625, 2025). "TLR2 is a well-known immune receptor of mast cells, and its downstream adaptor protein, MyD88, is significantly upregulated in rosacea lesions." (PMID 41383625, 2025). "As TLR/MyD88 signaling is necessary for proinflammatory cytokine activation, a link might exist between UV radiation and TLR/MyD88 signaling in the inflammatory cascades of rosacea as well." (PMID 27649161, 2016). "In summary, our study identifies the TLR2/MyD88/JAK2/STAT3 signaling pathway as a critical mediator of mast cell activation and degranulation in rosacea." (PMID 41383625, 2025). "The molecular mechanisms driving mast cell activation in rosacea remain poorly understood, though recent studies highlight the involvement of two key signaling pathways: the TLR2/MyD88 pathway and the Janus kinase/signal transducer and activator of transcription (JAK/STAT) pathway." (PMID 41383625, 2025).
sarcoma (3 papers, 2015 to 2021). A usually aggressive malignant neoplasm of the soft tissue or bone. "MyD88 has been shown to be required as well for the expansion of suppressive CD11b+Gr1+ cells, and MyD88-/- mice developed MCA induced sarcomas with decreased frequency." (PMID 26076008, 2015).
schizophrenia (3 papers, 2023 to 2025). A major psychotic disorder characterized by abnormalities in the perception or expression of reality. "Postmortem results show increased TLR4 protein expression in the prefrontal cortex of schizophrenia patients, which is associated with activation of the MyD88 and NF-κB pathways." (PMID 41346597, 2025). "Recent research has identified the TLR4/MyD88/NF-κB pathway as playing a central role in various neurological disease models, suggesting its relevance in schizophrenia pathogenesis." (PMID 41346597, 2025). "On the other hand, studies reported that antipsychotic-treated patients showed higher expression of tlr4 mRNA and myd88 mRNA in peripheral blood and postmortem brain tissue samples, respectively, over antipsychotic-free patients (schizophrenia)." (PMID 37627253, 2023). "Changes in the TLR downstream signalling proteins such as myd88 SNP (rs7744-3′UTR) were reported to be less prominent in patients with schizophrenia than in controls." (PMID 37627253, 2023). "Notably, increased TLR4 expression, myeloid differentiation primary response gene 88 (MyD88), and NF-кβ, which are components of the TLR4 signaling pathway, were detected in the prefrontal cortex of people with schizophrenia." (PMID 40153412, 2025).
Shock (3 papers, 2017 to 2021). The state in which profound and widespread reduction of effective tissue perfusion leads first to reversible, and then if prolonged, to irreversible cellular injury. "In the rat model of septic shock, LPS-induced hypotension, tachycardia, and inflammation was associated with increased MyD88 expression and phosphorylation of TAK1 and activation of NF-κB." (PMID 28415764, 2017). "Overall, these data demonstrate that interference with skeletal muscle fiber Myd88 signal transduction, directly or indirectly, results in marked reductions in the accumulation of cytokines and chemokines in the circulation during the early stages of septic shock." (PMID 33795743, 2021). "When the TNFAIP3, TNIP1, and MyD88 SNPs were included in the model, only the TNFAIP3 rs6920220 and TNIP1 rs3792783 SNPs were selected, and the predictive value significantly improved for discriminating between survivors and nonsurvivors shortly after septic shock onset (the first 28 days)." (PMID 30813592, 2019).
syphilis (3 papers, 2013 to 2025). A contagious bacterial infection caused by the spirochete Treponema pallidum. "It has been reported that the Toll-like receptor (TLR) and downstream MYD88 signaling pathway-mediated inflammatory response contributes to syphilis." (PMID 31358689, 2019).
tularemia (3 papers, 2014 to 2025). Tularemia is an infection caused by the bacterium Francisella tularensis. "Further, we found that cell-to-cell transfer in response to Francisella tularensis infection occurs in a predominantly MyD88-independent manner, relying on spleen tyrosine kinase (Syk) activity." (PMID 40313956, 2025). "Given our findings that F. tularensis targets TLR2- and MYD88-dependent signaling during macrophage infection, we next sought to determine the impact of this bacteria-host interplay in the mouse pneumonic tularemia model." (PMID 37404047, 2023). "Comparison of WT and ∆tolC LVS in the mouse pneumonic tularemia model revealed distinct roles for TLR2 and MYD88 in early responses to infection and host survival." (PMID 37404047, 2023). "Finally, experiments using the mouse pneumonic tularemia model revealed that both TLR2 and MYD88 signaling contribute to the early host response to LVS infection in vivo and to the protection against lethal infection." (PMID 37404047, 2023). "Experiments using the mouse pneumonic tularemia model confirmed the in vivo relevance of these findings, revealing contributions of TLR2 and MYD88 signaling to the protective host response to F. tularensis, which is modulated by the bacteria to promote virulence." (PMID 37404047, 2023). "Despite similar requirements for TLR2 and MYD88 in controlling intracellular replication of Francisella in macrophages, we found that MYD88 plays a more significant role in protection than TLR2 in the mouse pneumonic tularemia model." (PMID 37404047, 2023). "Notably, the LVS ∆tolC mutant regained full virulence in MYD88−/− mice, identifying a critical protective role for MYD88-dependent signaling in the pathogenesis of tularemia." (PMID 37404047, 2023).
Ureteral obstruction (3 papers, 2017 to 2022). Obstruction of the flow of urine through the ureter. "Altogether, our data demonstrate that sUA, released in the context of ureteral obstruction, is responsible for triggering inflammation and for consequent induction of fibrosis, in a Myd88- and Nlrp3- dependent manner." (PMID 28084303, 2017).
Acute hepatitis (2 papers, 2025). Acute hepatic injury resulting from inflammation typically accompanied by increased serum alanine transaminase activity. "In summary, CA-NPs exhibit significant hepatoprotective effects in the D-Gal and radiation-induced acute hepatitis rat model by inhibiting the MyD88/TLR4 pathway, providing experimental evidence for their clinical application in treating acute hepatitis." (PMID 40872532, 2025).
adenopathy (2 papers, 2022 to 2025). "Upon imaging, there was extensive, confluent retroperitoneal, pelvic, and left groin adenopathy, and a lymph node biopsy identified a CD20+ small B-cell neoplasm (MYD88-positive) with plasmacytic differentiation and marked AL amyloid deposition." (PMID 35096069, 2022).
African trypanosomiasis (2 papers, 2022 to 2025). "KEGG pathway enrichment analysis of these shared genes (corrected p < 0.05) revealed significant overrepresentation in glutamatergic synapse (encompassing HOMER1, HOMER2, PLCB4, and ADCY9) and African trypanosomiasis (containing SELE, MYD88, and PLCB4)." (PMID 41153960, 2025). "PBS and CLR test approaches have both indicated PSGs including IL12A, LAMA4, MYD88, SPAST and BOLA to confer resistance mechanisms towards the African trypanosomiasis and tick infestation." (PMID 35428239, 2022).
alcohol (2 papers, 2010 to 2021). "Animal models of alcohol-induced liver injury indicate that TLR2/Myd88 and TLR9/Myd88 signaling in hepatocytes is indispensable for neutrophil infiltration and liver injury." (PMID 34650994, 2021).
amyloid (2 papers, 2011 to 2015). "The involvement of Myd88 in animal models of amyloidosis remains controversial and somewhat conflicted." (PMID 25879763, 2015). "Interleukins and TNFα are critical cytokines in potentiating this immune response and are upregulated in settings of amyloid pathology; thus, we assessed their expression in Myd88−/− neuronal cultures." (PMID 25879763, 2015).
aneurysm (2 papers, 2022 to 2024). Bulging or ballooning in an area of an artery secondary to arterial wall weakening. "MyD88/TRIF pathway, which activates NF-κB accompanied by an excessive expression of inflammatory factors, is the major and key pathway accelerating aneurysm progression." (PMID 38284891, 2024). "TLR4/MyD88 KO mice had a reduction in aneurysm rupture rates but not in incidence of aneurysm formation." (PMID 36293468, 2022).